ENPEP (glutamyl aminopeptidase)
Description:
Regulates central hypertension through its calcium-modulated preference to cleave N-terminal acidic residues from peptides such as angiotensin II.
Synonyms: CD249; gp160; APA
Tractability: Small molecule: a drug acting on it is in phase 2 or 3 trials; a structure with a bound ligand is known; a high-quality ligand is known; it belongs to a druggable protein family. Antibody: UniProt places it where antibodies can reach, with high confidence; its Gene Ontology location is reachable by antibodies, with high confidence; UniProt predicts a signal peptide or a membrane-spanning region. PROTAC: its protein half-life has been measured; a small molecule that binds it is known.
Target class: Protease; Enzyme; Metallo protease; Metallo protease MAE clan; Metallo protease M1 family
Gene: Protein-coding gene on chromosome 4 (110,365,733 to 110,565,285, forward strand). Ensembl gene ENSG00000138792.
Subcellular location: Cell membrane
Pathways (Reactome):
Metabolism of proteins: Metabolism of Angiotensinogen to Angiotensins
Gene Ontology:
Molecular function: aminopeptidase activity; glutamyl aminopeptidase activity; metalloaminopeptidase activity; metallopeptidase activity; peptidase activity; zinc ion binding
Biological process: cell migration; cell population proliferation; regulation of systemic arterial blood pressure by renin-angiotensin; angiogenesis; angiotensin maturation; cell-cell signaling; glomerulus development; peptide catabolic process; proteolysis
Cellular component: extracellular exosome; lysosomal membrane; plasma membrane; apical part of cell; apical plasma membrane; brush border; cytoplasmic vesicle; external side of plasma membrane
Genetic constraint (gnomAD): Loss-of-function variants: 85 observed, 99.18 expected, observed/expected ratio (o/e) 0.86, 90% interval 0.72 to 1.03. The upper end of that interval is the gene's LOEUF score, 1.03, which puts it in group 4 of 6, group 1 being the genes least tolerant of losing a copy. Missense variants: 1,067 observed, 1,075.1 expected, observed/expected ratio (o/e) 0.99, 90% interval 0.94 to 1.04. Synonymous variants: 382 observed, 397.39 expected, observed/expected ratio (o/e) 0.96, 90% interval 0.88 to 1.05.
Homologues: Orthologues: chimpanzee ENPEP (98% identical), macaque ENPEP (97% identical), pig ENPEP (84% identical), dog ENPEP (83% identical), rat Enpep (78% identical), rabbit ENPEP (78% identical), mouse Enpep (77% identical), guinea pig ENPEP (69% identical), tropical clawed frog enpep (61% identical), zebrafish enpep (58% identical), Drosophila melanogaster CG32473 (39% identical), Drosophila melanogaster CG8773 (37% identical), and 1 more. Paralogues in human: ANPEP (33% identical), ERAP2 (32% identical), ERAP1 (31% identical), LNPEP (31% identical), NPEPPS (30% identical), LVRN (28% identical), TRHDE (26% identical), LTA4H (12% identical), RNPEP (12% identical), RNPEPL1 (12% identical), AOPEP (10% identical).
Diseases named in the same sentence as ENPEP in open-access papers:
ENPEP is named in the same sentence as 61 diseases in open-access papers, as found by Europe PMC text mining. Sharing a sentence is not in itself a finding about the gene and the disease. The quoted sentences say what the papers report.
Hypertension (18 papers, 2005 to 2025). The presence of chronic increased pressure in the systemic arterial system. "We then sought to provide an orthogonal replication of these findings using a rare ENPEP variant (rs33966350) associated with hypertension in previous GWAS21." (PMID 38504097, 2024). "We used the eQTL information of all the tissues and finally identified three key genes associated with essential hypertension: ENPEP, USP38, and KCNK3." (PMID 36845374, 2023). "The human ortholog of CG8773/CG8774 is predicted to be ENPEP, a member of the renin-angiotensin system that controls blood pressure and hypertension; known risk factors for atrial fibrillation (AF)." (PMID 33561224, 2021). "ENPEP is found to be a candidate gene associated with obesity and hypertension traits in GWAS (Genome Wide Association study) studies." (PMID 32027667, 2020). "We also identified independent missense associations for genes and phenotypes such as ENPEP and hypertension; GSDMB and asthma; IFIH1 and hypothyroidism; and PALB2 and lung cancer." (PMID 29691392, 2018). "ENPEP, as part of the renin-angiotensin system, has been shown to control blood pressure, and hypertension is a known risk factor for AF." (PMID 25888893, 2015). "A human GWAS has shown that a common SNP in ENPEP, rs6825911, is associated with hypertension in East Asians." (PMID 24465984, 2014). "ENPEP was found to be associated with hypertension in a genome-wide association study in humans." (PMID 36845374, 2023). "The gene ENPEP had been found to be associated with hypertension in a meta-analysis." (PMID 36845374, 2023). "In previous GWAS studies on blood pressure regulation, the association of ENPEP and KCNK3 with hypertension has been established, and the association between USP38 and blood pressure regulation still needs further validation." (PMID 36845374, 2023). "Other studies involved in treating hypertension in animal models using inhibitors to block ENPEP activity have also supported a direct link between ENPEP and arterial hypertension in the body." (PMID 29900035, 2017). "ENPEP plays a role in the catabolic pathway of the renin-angiotensin system and is a major contributor to the development of clinical arterial hypertension in the body." (PMID 29900035, 2017). "Currently, inhibition of ENPEP activity is one of procedure used to treat hypertension condition." (PMID 32027667, 2020). "ENPEP is involved in the catabolic pathway of the Renin-angiotensin System (RAS) forming angiotensin III, which participates in blood pressure regulation and blood vessel formation, and may contribute to risk of atrial fibrillation, angiogenesis, hypertension and tumorigenesis." (PMID 29900035, 2017). "This gene-based association approach with tissue specificity has a lower multiple-testing burden and has identified three key genes in essential hypertension: potassium two-pore domain channel subfamily K member 3 (KCNK3), glutamyl aminopeptidase (ENPEP), and ubiquitin-specific peptidase 38 (USP38)." (PMID 38786976, 2024).
breast carcinoma (10 papers, 2013 to 2023). "Besides this, ID4, SEMA3F, FOXD, KCNK5, WNK4 and ECM1 associate with chemoresistance origin and SOX5, ITM2A, SNCG, EPHA4, NTS, FGFR2 and ENPEP associate moreover with breast cancer tumorigenesis." (PMID 37239828, 2023). "For example, ENPEP has been shown to be a key factor involved in breast cancer cell proliferation through the function of inducing G2/M cell cycle arrest and reducing anchorage-independent cell growth of mammary origin." (PMID 36936167, 2023). "miR-125b has a tumor suppressor role by targeting the 3’ untranslated region (UTR) of mRNA of glutamyl aminopeptidase encoding gene ENPEP, as well as mRNA of Casein Kinase 2-α (CK2-α) which are involved in breast cancer tumorigenesis." (PMID 32040529, 2020). "When ENPEP is silenced, the occurrence of breast cancer can be inhibited; moreover, both in vitro and in vivo, ENPEP silencing and impaired ENPEP activity reduce the proliferation, migration and drug resistance of colorectal cancer." (PMID 32509568, 2020). "Our data suggest that in some percentage of patients with breast cancer tumors, miR-125b downregulation consistently occurs; this involves a repression of the genes that code for ENPEP and CK2-α, and potentially MEGF9 and CCNJ." (PMID 24098452, 2013). "Moreover, we discovered that ENPEP is overexpressed in a relatively high percentage of breast cancer patients (56%)." (PMID 24098452, 2013). "In consistent with these reports, miR-125b was found to exert its anti-tumor activity via regulating ENPEP (aminopeptidase A), CK2-α (casein kinase 2 alpha), CCNJ (cyclin J) and MEGF9 (multiple EGF-like-domains 9) in breast cancer." (PMID 25605244, 2015). "Analysis of ENPEP, CK2-α, CCNJ, and MEGF9 protein expression in breast cancer patients revealed that they were overexpressed in 56%, 40–56%, 20%, and 32% of the tumors, respectively." (PMID 24098452, 2013). "To investigate the importance of ENPEP, CK2-α, CCNJ, and MEGF9 proteins in breast tumors, we studied the expression of each protein by western blot analysis in 25 breast cancer patient samples (series 3)." (PMID 24098452, 2013). "The expression of ENPEP and CK2-α was inversely correlated with miR-125b expression in breast tumors, indicating the relevance of these potential oncogenic proteins in breast cancer patients." (PMID 24098452, 2013). "Apart from the overexpression of ENPEP, CK2-α, CCNJ, and MEGF9 in certain breast cancer patients, the potential oncogenic roles of these proteins is supported by the fact that their downregulation causes significant inhibition of cell proliferation." (PMID 24098452, 2013). "Finally, we analyzed the protein expression of ENPEP, CK2-α, CCNJ, and MEGF9 in breast cancer patients." (PMID 24098452, 2013). "In addition, correlation analysis between miR-125b levels (analyzed with qRT-PCR) and the expression of ENPEP, CK2-α, CCNJ, and MEGF9 protein was studied in 25 breast cancer patient samples (series 3)." (PMID 24098452, 2013). "In particular, our results show that restoration of miR-125b expression or knockdown of ENPEP, CK2-α, CCNJ, or MEGF9 may provide novel approaches for the treatment of breast cancer." (PMID 24098452, 2013). "Glutamyl aminopeptidase (ENPEP), casein kinase II subunit α (CK2-α), cyclin J (CCNJ), and multiple epidermal growth factor-like-domains 9 (MEGF9) are additional miR-125b targets that are upregulated in human breast cancer samples and may contribute to tumor progression." (PMID 24774301, 2014).
COVID-19 (6 papers, 2021 to 2024). A disease caused by infection with severe acute respiratory syndrome coronavirus 2. "Many follow-up studies have reported ABO and ENPEP as COVID-19 risk genes; however, the evidence for the FUT2 gene is conflicting." (PMID 35736459, 2022). "ENPEP mRNA expression in various tissues was further investigated in relation to age, an important prognostic factor for COVID-19." (PMID 39661628, 2024). "We explored the association of coronavirus receptors with GBM and identified ANPEP and ENPEP as potential biomarkers and therapies for COVID-19 and GBM." (PMID 35464443, 2022). "mGWAS-Explorer was also able to identify ENPEP and FUT2 as potential candidate genes for COVID-19, although the association signal of these two genes were below the genome-wide significance threshold in the original study." (PMID 35736459, 2022). "Heatmaps revealed several COVID-19-related genes (38 out of 159 total) that were dysregulated by one or more of the HFDs, including Ace2 (angiotensin-converting enzyme 2) and Enpep (glutamyl aminopeptidase)." (PMID 38151490, 2023). "ENPEP and ACE2 both have important roles in the RAAS, with RAAS dysregulation suggested as an important part of COVID-19 pathophysiology." (PMID 39661628, 2024). "As this study provides an initial bioinformatics characterization, further experimental studies are merited which directly test the role of ENPEP as a potential co-factor in SARS-CoV-2 infection, and the roles of ENPEP and ACE2 in RAS/RAAS in COVID-19 pathophysiology." (PMID 39661628, 2024). "Our work explores for the first time the association of coronavirus receptors with GBM and suggests ANPEP and ENPEP as potential therapeutic targets of GBM irrespective of COVID-19." (PMID 35464443, 2022).
colorectal cancer (5 papers, 2017 to 2023). A primary or metastatic malignant neoplasm that affects the colon or rectum. "ENPEP is positively correlated with the aggressiveness of colorectal cancer, and overexpression of ENPEP promotes cell migration." (PMID 38062443, 2023). "ENPEP functions in tumor proliferation, migration, and drug resistance in breast and colorectal cancers." (PMID 35288483, 2022). "ENPEP has also been identified as one of the genes involved in the four‐gene model for the prediction of prognosis in colorectal cancer." (PMID 34510798, 2021). "Aminopeptidase A (APA; also known as ENPEP) was selected as our focus because its relationship with colorectal cancer requires clarification." (PMID 28177885, 2017).
renal carcinoma (4 papers, 2010 to 2023). A carcinoma arising from the epithelium of the renal parenchyma or the renal pelvis. "Recent studies revealed that other SARS-CoV-2 factors such as ANPEP (alanyl aminopeptidase, membrane), ENPEP (glutamyl aminopeptidase), and DPP4 (dipeptidyl peptidase 4) are expressed at high levels in renal cancer, especially in ccRCC." (PMID 38255667, 2023). "We further analyzed the expression of ACE2, ANPEP, ENPEP, DPP4, and TMPRSS2 gene in renal carcinoma tissues." (PMID 33330620, 2020). "Further analysis of renal carcinoma subtypes revealed that KIRP and KIRC tumors exhibit increased levels of DPP4, ANPEP, and ENPEP along with ACE2 receptors." (PMID 33330620, 2020).
renal tumor (4 papers, 2010 to 2024). "Fittingly, ENPEP has been connected to a variety of cancers and is upregulated in colorectal and renal neoplasms." (PMID 39661628, 2024).
atrial fibrillation (3 papers, 2015 to 2021). A disorder characterized by an electrocardiographic finding of a supraventricular arrhythmia characterized by the replacement of consistent P waves by rapid oscillations or fibrillatory waves that vary in size, shape and timing and are accompanied by an irregular ventricular response. "Genome wide association studies have examined blood pressure variation and atrial fibrillation risk in human populations and identified an association with ENPEP variants." (PMID 29900035, 2017). "Our data suggest that de-regulation of both PITX2 and ENPEP could contribute to an increased risk of atrial fibrillation in carriers of disease-associated variants, and show the challenges that we face in the functional analysis of genome-wide disease associations." (PMID 25888893, 2015).
glioblastoma (3 papers, 2022 to 2024). The most malignant astrocytic tumor (WHO grade IV). "In fact, the BS149 cell line generated from recurrent glioblastoma is more malignant than the other four glioblastoma cell lines (LN018, LN215, LN229, and LN319) and has higher mRNA levels of DPP4, ANPEP, and ENPEP, further corroborating the potential oncogenic roles of ANPEP and ENPEP in GBM." (PMID 35464443, 2022). "Because ISH staining for the prototypical endothelial marker CD31 (PECAM1) is not available in the Ivy GAP, analysis of glioblastoma vasculature considered ESM1, MECOM, and ENPEP; genes known to be enriched in endothelial cells." (PMID 39724753, 2024).
melanoma (3 papers, 2020 to 2022). A malignant, usually aggressive tumor composed of atypical, neoplastic melanocytes. "We also found that melanoma patients with ENPEP mutations had longer OS (28.1 vs. 15.5 months) than wild‐type melanoma patients; however, the result was not significant (p = 0.064)." (PMID 34862755, 2022).
Obesity (3 papers, 2018 to 2020). Accumulation of substantial excess body fat. "We have recently detected obesity-associated significant decrease of membrane-bound AP-A (glutamyl aminopeptidase) activity in the skeletal muscle of Zucker rats accompanied by elevated plasma AP-A activity suggesting stimulated tissue AP-A autolysis due to dyslipidemia in obese phenotype." (PMID 33344504, 2020). "Among 8 unreported SSGs, the highly connected genes with obesity related genes is ENPEP followed by WNK1." (PMID 32027667, 2020). "Regarding skeletal muscle glutamyl aminopeptidase (AP-A), which is disregulated in obesity, both Enpep mRNA level and AP-A activity were significantly upregulated in this tissue in obese Zucker rats after the treatment." (PMID 33344504, 2020). "Therefore, our work provides strong evidence for ENPEP to be a novel gene that contributing to obesity." (PMID 32027667, 2020). "The aim of this study was to investigate if urinary glutamyl aminopeptidase (GluAp), alanyl aminopeptidase (AlaAp), Klotho and hydroxyproline can be considered as potential biomarkers of renal injury and fibrosis in an experimental model of obesity." (PMID 30483154, 2018).
asthma (2 papers, 2018 to 2022). "Our study revealed an increased expression of ENPEP in the asthma and COPD epithelium triple co-cultures exposed to UPM." (PMID 36012391, 2022). "PCR analysis showed that mRNA expression of BPIFA2 and ENPEP was upregulated in both asthma and COPD, while the expression of CYP1B1-AS1 and TIPARP was increased in the epithelium from COPD patients only." (PMID 36012391, 2022). "We showed that the most potently activated genes after air pollution exposure in the triple co-cultured epithelium of asthma and COPD patients were BPIFA2 and ENPEP, while CYP1B1-AS1 and TIPARP were upregulated in the COPD epithelium only." (PMID 36012391, 2022). "We found that the mRNA expression of BPIFA2 and ENPEP was upregulated after UPM treatment, most potently in triple co-cultures of the asthma and COPD patients only." (PMID 36012391, 2022).
hepatocellular carcinoma (2 papers, 2023 to 2025). A malignant tumor that arises from hepatocytes. "Moreover, the expression of PPP1R1B, TMEM45B, AFP, and ENPEP followed the same pattern in vitro using human hepatoma (HEPG2) and mouse liver 12 (AML12) cell lines incubated with squalene, indicating a direct effect of squalene on these expressions." (PMID 37628732, 2023). "Furthermore, a study on hepatocellular carcinoma reported that ID decreased ENPEP expression and promoted angiogenesis and metastasis through the transcription factor SP1, providing additional insight into how ID may enhance hepatocellular carcinoma progression." (PMID 41190142, 2025).
lung carcinoma (2 papers, 2018 to 2021). "The first gene near the second DMR was PITX2, whose low methylation correlated with higher risk of lung cancer progression, and the other was ENPEP that was under-expressed in lung adenocarcinoma." (PMID 34262872, 2021).
squamous cell carcinoma (2 papers, 2020 to 2025). A carcinoma arising from squamous epithelial cells. "Squamous cell carcinoma is linked to the expression of MARCKS, CD36, DAB2, ENPEP, and TIMP1." (PMID 40565366, 2025).
acute kidney injury (1 paper, 2024). Sudden and sustained deterioration of the kidney function characterized by decreased glomerular filtration rate, increased serum creatinine or oliguria. "In a previous study of our group using cisplatin-treated rats, we showed that the content of glutamyl aminopeptidase (GluAp), an enzyme derived from tubular epithelium, was increased in microvesicular and exosomal fractions of urine and could serve as an early biomarker of acute kidney injury." (PMID 39767742, 2024).
breast tumors (1 paper, 2013). "The aim of analyzing ENPEP, CK2-α, CCNJ, and MEGF9 expression in breast tumors was to clarify their association with miR-125b." (PMID 24098452, 2013). "Remarkably, miR-125b is inversely correlated with ENPEP and CK2-α expression in breast tumors." (PMID 24098452, 2013).
cervical intraepithelial neoplasms (1 paper, 2013). "In addition, ENPEP is expressed in neoplastic lesions of the uterine cervix, and its levels are upregulated as the lesions progress from cervical intraepithelial neoplasms to invasive squamous cell carcinomas." (PMID 24098452, 2013).
choriocarcinoma (1 paper, 2025). An aggressive malignant tumor arising from trophoblastic cells. "Choriocarcinoma is associated with MARCKS, DAB2, ENPEP, and TIMP1." (PMID 40565366, 2025).
hydatidiform mole (1 paper, 2025). A gestational trophoblastic disorder characterized by marked enlargement of the chorionic villi, hyperplasia of the villous trophoblastic cells and hydropic changes. "Complete hydatidiform mole is associated with the DAB2 and ENPEP genes." (PMID 40565366, 2025).